ANGPTL4 (angiopoietin like 4)
Diseases named in the same sentence as ANGPTL4 in open-access papers (continued):
Sharing a sentence is not in itself a finding about the gene and the disease.
diabetes (continued). "Due to the increasing rate of diabetes and the importance of ANGPTL3 and ANGPTL4 in the pathogenesis of diabetes through possible association with metabolic syndrome, it seems there is a relationship between these glycoproteins with metabolic syndrome especially in patients with diabetes." (PMID 38140923, 2023). "Beyond oncology, ANGPTL4 has also been implicated in STAT3 regulation in polycystic ovary syndrome and diabetes, indicating its broader role in modulating JAK/STAT3 signaling across diseases." (PMID 40616161, 2025). "Single-cell sequencing analysis revealed heterogeneities of ECs and CMs in diabetes, Angptl4-Cdh5 and Angptl4-Sdc3 were involved in the communication between ECs and CMs in diabetes." (PMID 40296165, 2025). "Our data demonstrate that Angptl4 expression is up-regulated, and LPL expression and its associated activities are down-regulated, in fibrotic kidneys during diabetes." (PMID 39630889, 2024). "It is clear from these data that Angptl4 is one of the catalysts of renal fibrosis in diabetes and leads to disruption of cytokine and chemokine homeostasis by up-regulating TGFβ signaling." (PMID 39630889, 2024). "To investigate why DPP-4 and Angptl4 levels were elevated in diabetes, we performed miRNA array analysis in control and diabetic mice." (PMID 39630889, 2024). "Here, we show that elevated TG levels (lipid load) due to defects in lipid oxidation in mitochondria can be mitigated by loss of Angptl4, which reduced lipid load, restored mitochondrial structure and function, and restored FAO in diabetes." (PMID 39630889, 2024). "We show that both podocyte- and tubule-specific ANGPTL4 are crucial fibrogenic molecules in diabetes." (PMID 39630889, 2024). "Among the top upregulated genes in response to HFD/STZ-induced diabetes within each cell population were transcripts for Pdk4, Angptl4, Txnip, Postn, Hmgcs2, and Ucp3, of which several have been previously involved in heart failure." (PMID 37010266, 2023). "The urinary concentration of ANGPTL-4 was positively correlated with age, duration of diabetes, FPG, HbA1c, urea, serum creatinine, urine albumin, and UACR in all three groups." (PMID 37108963, 2023). "Increasing age, sex, higher body mass index, smoking, diabetes, hypertension, elevated ANGPTL3 and decreased ANGPTL4 had a statistically significant association with atherosclerosis development in the univariable analysis." (PMID 34742313, 2021). "Lastly, in addition to this main contribution on the potential benefits of the ANGPTL8 PTV, our study also found associations between the ANGPTL4 PTV and a lower risk of T2D, as well as multiple diabetes-related disease endpoints." (PMID 33909604, 2021). "Maintaining a LPL- ANGPTL4 balance is essential, and considering LPL and ANGPTL4 as cardiac specific biomarkers would be advantageous in detecting the stage of diabetes and in treating cardiovascular complications accordingly." (PMID 34616362, 2021). "Tan and Chong demonstrated that the dermal treatment of the recombinant protein of angiopoietin-like 4 (ANGPTL4) promoted wound healing in mice afflicted with diabetes." (PMID 32611449, 2020). "We assess the selection performance of POINT using simulations and illustrate how it can be used to prioritize individual rare variants in PCSK9, ANGPTL4 and CETP in the Action to Control Cardiovascular Risk in Diabetes (ACCORD) clinical trial data." (PMID 30779729, 2019). "In this regard, the multiple regression model indicates that increased levels of IGFBP1 and TG are strong predictors of a rise in circulating ANGPTL4, which consequently indicates a state of nephropathy in people with diabetes." (PMID 31772941, 2019). "This would promote the use of ANGPTL4 as a biochemical marker for the detection of nephropathy in patients with diabetes." (PMID 31772941, 2019).
diabetes (continued). "Using a multiple regression model, we showed that the increased levels of IGFBP1 and TG are strong predictors of a rise in circulating ANGPTL4, which consequently indicates a state of nephropathy in people with diabetes." (PMID 31772941, 2019). "ANGPTL4 remained positively associated with hsCRP when taking account of age, sex, NEFA, total cholesterol, triglycerides and the presence of diabetes (Model A1) or alternatively of fasting glucose (Model A2)." (PMID 29587751, 2018). "ANGPTL4 plasmatic levels decreased by insulin playing a key role in type 2 diabetes mellitus and metabolic syndrome." (PMID 29389861, 2018). "Accordingly, the plasma ANGPTL4 concentration is likely to be elevated in subjects with pro-inflammatory conditions such as the metabolic syndrome and Type 2 diabetes mellitus (T2DM)." (PMID 29587751, 2018). "In conclusion, CMs and ECs exhibit significant heterogeneities and their metabolism processes are affected in diabetes, and Angptl4 may participate in the cell communication between ECs and CMs by regulating lipid metabolism." (PMID 40296165, 2025). "Prediabetes and diabetes were independently associated with higher serum ANGPTL4, whereas the presence of hepatic steatosis was not." (PMID 41226996, 2025). "Diabetes was induced in control and Angptl4−/− mice with STZ for 20 weeks." (PMID 39630889, 2024). "Differentially regulated genes not overlapping with ERCB data also reflected diabetes-associated changes, such as extracellular matrix (ANGPTL4, TNN, DPT, COL9A2) or gestational diabetes (LAT2, HP, CXCL10, CD86, CD68, REN, SLC2A3, VCAM1)." (PMID 33923831, 2021). "Finally, we showed that the PTVs in ANGPTL4 and ANGPTL8 were associated with lower risks of diabetes-related endpoints and statin therapy respectively." (PMID 33909604, 2021). "In contrast, an earlier study reported that serum ANGPTL4 levels are significantly lower in patients with type 2 diabetes mellitus compared with healthy adults and circulating ANGPTL4 levels were negatively associated with plasma glucose and insulin resistance by HOMA IR in humans." (PMID 32878157, 2020). "In this study, we wanted to explore a potential correlation between IGFBP1 and ANGPTL4 under conditions of T2D alone and DN, where a rise in ANGPTL4 levels would be permissive for the development of a kidney condition as a complication of diabetes." (PMID 31772941, 2019). "We also apply POINT to the Action to Control Cardiovascular Risk in Diabetes (ACCORD) clinical trial data, finding promising rare variants in PCSK9, ANGPTL4 and CETP that may be associated with lipoprotein-related outcomes." (PMID 30779729, 2019). "We intend to demonstrate whether TXL can attenuate myocardial I/R injury in diabetes, characterized with microvascular endothelial barrier disruption, by induction of Angptl4-mediated protection of endothelial barrier integrity." (PMID 29912977, 2018). "Furthermore, ANGPTL4 has recently been demonstrated to be an important factor in diabetes-induced angiogenesis in PDR28,29." (PMID 29626212, 2018). "Moreover, ANGPTL4 expression in a transgenic mice model of diabetes appears to improve angiogenesis thus accelerating wound re-epithelialization." (PMID 29389861, 2018). "A recent study focused on the evaluation of the systemic effect of insulin on LPL and its regulative machinery in subjects with a different tolerance degree to insulin and showed a decrease in the adipose tissue ANGPTL4 expression in type 2 diabetes mellitus patients and healthy subjects." (PMID 28182091, 2017). "ANGPTL3 was associated with ANGPTL8 in the non-diabetic subjects, whereas, ANGPTL4 was associated with ANGPTL8 in the obese subjects regardless of their diabetes status." (PMID 27733177, 2016). "Moreover, PCSK5 might be a potential target to lower LDL levels and valuable for the ANGPTL4 (angiopoietin like 4)-mediated target therapy of diabetes and metabolic syndrome." (PMID 38483771, 2024).
diabetes (continued). "Finally, we tested the therapeutic effect of the anti-mouse ANGPTL4 antibody on diabetes mice." (PMID 37217704, 2023). "Knockdown of ANGPTL4 accelerates the catabolism of TRL and increases the oxidation and uptake of FA in brown adipocytes (BAT), At the same time, it can regulate diabetes by regulating glucose metabolism." (PMID 40296165, 2025). "The existing evidence on ANGPTL-4 and KIM-1 as biomarkers of diabetes-related kidney damage among Indians is limited and consequently requires further investigation." (PMID 37108963, 2023). "Increased serum levels of ANGPTL-4, syndecan-1, PIGF, and IL-8 were observed in diabetes patients with complications." (PMID 34650995, 2021). "On the other hand a significant correlation is found between the ANGPTL4 concentration and FFA levels in subjects with type 2 diabetes mellitus (T2DM) compared to healthy individuals." (PMID 31164103, 2019). "In contrast, in our cohort the presence of hepatic steatosis did not modify the elevation of serum ANGPTL4 observed in participants with prediabetes and diabetes." (PMID 41226996, 2025). "In addition, angiopoietin-like protein 4 (ANGPTL4), which is upregulated by metabolic demand, has been shown to be involved in the pathogenesis of angiogenesis of the placenta and diabetes-related complications and also to promote the metastasis of MM." (PMID 39940783, 2025). "We observed significantly higher serum ANGPTL4 concentrations in individuals with prediabetes and diabetes, irrespective of steatosis status." (PMID 41226996, 2025). "Taken together, we observed higher circulating ANGPTL4 concentrations in individuals with prediabetes and diabetes, irrespective of hepatic steatosis." (PMID 41226996, 2025). "Furthermore, the regulation of ANGPTL4 expression by HIF-1α has been confirmed in various diseases, such as tumors, diabetes, and arterial sclerosis resulting from chronic intermittent hypoxia." (PMID 38992710, 2024). "Results of the study indicated that obese patients without or with type 2 diabetes mellitus had elevated levels of the ANGPTL4 rather than the healthy control individuals." (PMID 38140923, 2023). "Although the number of patients with diabetes in the CAD group was higher than that in the non-CAD group, ANGPTL4 expression in EAT was not significantly altered in patients with or without diabetes." (PMID 35566578, 2022). "Increased ANGPTL4 levels correlated positively with IGFBP1 in people with diabetes with and without nephropathy." (PMID 31772941, 2019). "Diabetes accelerates the fibrogenic phenotype in control mice but not in ANGPTL4 mutant mice." (PMID 39630889, 2024). "In subsidiary analyses with BMI in addition to age, sex, the presence of diabetes, NEFA, total cholesterol and triglycerides as dependent variables, plasma PLTP activity but not ANGPTL4 was independently associated with BMI (β = 0.239, p = 0.05 and β = 0.137, p = 0.23, respectively; data not shown)." (PMID 29587751, 2018). "Taken altogether, at a condition of diabetes both with and without nephropathy, IGFBP1 was found to be a marker and a significant predictor with the dependent variable ANGPTL4." (PMID 31772941, 2019). "Taken altogether, at a condition of diabetes both with and without nephropathy, IGFBP1 was found as a marker and a significant predictor with the dependent variable ANGPTL4." (PMID 31772941, 2019).
type 2 diabetes (54 papers, 2012 to 2025). "ANGPTL4 inhibitors show promise for treating lipid disorders associated with metabolic syndrome, type 2 diabetes, and familial hyperlipidemia, with preclinical development currently underway." (PMID 39811640, 2025). "While numerous studies have linked serum levels of ANGPTL4 to body mass index, particularly in the context of type 2 diabetes, the source and functional significance of ANGPTL4 expression remain poorly understood." (PMID 40652248, 2025). "Data from human genetic studies have demonstrated that loss-of-function mutations in the Angptl4 locus are linked to reduced type 2 diabetes and risk of cardiovascular disease." (PMID 39630889, 2024). "The effect of the loss-of-function (LOF) ANGPTL4 mutation on the risk of ischemic heart disease and type-2 diabetes was assessed." (PMID 36614969, 2022). "Cardiovascular disease is a co-morbidity in psoriasis, and ANGPTL4 has been strongly linked with the development of atherosclerosis and type 2 diabetes." (PMID 35860030, 2022). "Accumulating evidence indicates that Angiopoietin-like 4 (ANGPTL4) is associated with the risk of atherosclerosis and type 2 diabetes." (PMID 35807360, 2022). "ANGPTL4 is directly associated with the risk of atherosclerosis and type 2 diabetes mellitus (T2DM)." (PMID 34820432, 2021). "There is evidence that ANGPTL4 is directly related to the risk of type 2 diabetes and insulin resistance in an animal model." (PMID 32878157, 2020). "In conclusion, this study demonstrates that VAT ANGPTL4 overexpression is associated with local metabolic impairment and inflammation and predicts impaired glucose regulation and type 2 diabetes in obese individuals." (PMID 33003532, 2020). "Along with protecting from dyslipidemia, the inactivating variant E40K of the ANGPTL4 gene is associated with reduced risk of type 2 diabetes (T2D)." (PMID 33003532, 2020). "Another study found that gain-of-function alleles of LPL and loss-of-function alleles of ANGPTL4 were associated with lower risk of type 2 diabetes." (PMID 29502266, 2018). "We find that p.E40K in ANGPTL4 is associated with lower fasting glucose and greater insulin sensitivity in humans, as well as reduced risk of type 2 diabetes." (PMID 29899519, 2018). "Here, the authors find that predicted loss-of-function variants in ANGPTL4 are associated with glucose homeostasis and reduced risk of type 2 diabetes and that Angptl4−/− mice on a high-fat diet show improved insulin sensitivity." (PMID 29899519, 2018). "Other rare predicted loss-of-function variants in ANGPTL4 are also associated with lower risk of type 2 diabetes, providing additional allelic evidence that genetic loss of ANGPTL4 function improves glucose homeostasis in humans." (PMID 29899519, 2018). "We describe ANGPTL4 as a gene in which loss-of-function variants confer protection from both coronary atherosclerosis and type 2 diabetes." (PMID 29899519, 2018). "Angptl4-deficient mice manifest greater insulin sensitivity and improved glucose homeostasis, further supporting for the conclusion that genetic inactivation of ANGPTL4 improves glucose homeostasis and reduces risk of type 2 diabetes." (PMID 29899519, 2018). "Collectively, these findings indicate that genetic variants that abolish ANGPTL4 function are associated with improved insulin sensitivity and glucose homeostasis and reduced risk of type 2 diabetes in humans." (PMID 29899519, 2018). "In conclusion, we found that loss-of-function variants in ANGPTL4 were associated with increased insulin sensitivity and reduced risk of type 2 diabetes, mirroring the beneficial effects on glucose homeostasis of deletion of Angptl4 in mice." (PMID 29899519, 2018). "We examined associations of ANGPTL4 p.E40K with type 2 diabetes defined by an Electronic Health Record (EHR) algorithm in the DiscovEHR study." (PMID 29899519, 2018).
type 2 diabetes (continued). "The 40Lys variant in ANGPTL4 was associated with protection from coronary disease and type 2 diabetes in groups with genetically higher or lower LDL-C." (PMID 30326043, 2018). "So, the two genotypes of ANGPTL4 variants play a protective role against CVD in Tunisian type 2 diabetic patients." (PMID 27004807, 2016). "In addition, human genetic inactivation of ANGPTL4 has been shown to improve glucose homeostasis and reduce type 2 diabetes risk." (PMID 40511612, 2025). "Therapies targeting ANGPTL4 levels are expected to favourably impact the risk of Type 2 diabetes." (PMID 38895109, 2024). "ANGPTL4 is linked with triglyceride and high-density lipoprotein cholesterol levels; hence it could be related to the higher risk of type 2 diabetes in SCZ patients treated with clozapine drug." (PMID 36405929, 2022). "It is not yet known whether p.E40K affects glucose homeostasis in non-diabetics, whether other variants that abolish ANGPTL4 function modify type 2 diabetes risk, or how loss of ANGPTL4 function modifies glucose homeostasis and type 2 diabetes risk." (PMID 29899519, 2018). "In this genetic association study including 392 220 people, triglyceride-lowering alleles in LPL or its inhibitor ANGPTL4 were associated with lower risk of coronary artery disease and type 2 diabetes in a consistent fashion across quantiles of the population distribution of LDL-C–lowering alleles." (PMID 30326043, 2018). "Together, these observations suggest that genetic inhibition of ANGPTL4 function might have a favorable impact on glucose homeostasis in humans and reduce risk of type 2 diabetes." (PMID 29899519, 2018). "We used a two-sided exact conditional test to combine the counts across studies given the low number of type 2 diabetes cases co-occurring with ANGPTL4 pLoFs, finding 29% lower odds of type 2 diabetes among carriers of pLoF variants (OR 0.71, 95% CI 0.49–0.99, p = 0.041)." (PMID 29899519, 2018). "Whether the association of genetic variants that inactivate ANGPTL4 with reduced type 2 diabetes risk is mediated exclusively via modulation of lipoprotein lipase activity or involves other mechanisms remains to be clarified." (PMID 29899519, 2018). "This hypothesis is supported by a recent report of reduced type 2 diabetes risk associated with the p.E40K variant that abolishes ANGPTL4 ability to inhibit LPL14,15." (PMID 29899519, 2018). "We hypothesize that loss of ANGPTL4 function might improve glucose homeostasis and decrease risk of type 2 diabetes (T2D)." (PMID 29899519, 2018). "To understand whether ANGPTL4 pLoF variants were also associated with type 2 diabetes, we evaluated the prevalence of pLoFs in ANGPTL4 in exome sequence data from 32,015 type 2 diabetes cases and 84,006 controls in six population case–control studies." (PMID 29899519, 2018). "Another gene that has been associated with type II diabetes and shows higher gene transcript levels in DD, is angiopoietin-like 4 (ANGPTL4), a glycosylated, secreted protein with a fibrinogen C-terminal domain involved in glucose homeostasis, lipid metabolism and insulin sensitivity." (PMID 23554969, 2013). "Interestingly, circulating ANGPTL4 levels were found to be elevated in obese patients with different metabolic phenotypes, i.e., metabolically unhealthy, type 2 diabetes (T2D), and metabolically healthy, and this was associated with endothelial dysfunction, an early abnormality in atherosclerosis." (PMID 36074318, 2022). "The serum levels of Angiopoietin-like proteins (ANGPTL) 3, ANGPTL4, betatrophin, angiopoietin 1 and 2 were measured in 50 type 2 diabetic patients and 67 DN patients compared to 117 healthy participants." (PMID 39030467, 2024). "A study of 93 patients with type 2 diabetes and 99 healthy adult controls found that ANGPTL3/8 levels were similar between type 2 diabetes patients and controls, whereas ANGPTL4/8 levels were about twofold higher in patients." (PMID 38160757, 2023).